BCL2 (BCL2 apoptosis regulator)
Diseases named in the same sentence as BCL2 in open-access papers (continued):
Sharing a sentence is not in itself a finding about the gene and the disease.
lymphoma (continued). "It has also been established that this combination effectively promotes apoptosis in MYC/BCL2 co-expressing lymphoma cells and enhances T-cell responses in DLBCL." (PMID 40722681, 2025). "In fact, CD34 + cells have similar levels of BCL2 to lymphoma cell lines due to their immaturity but were not as dramatically affected by VEN." (PMID 39531065, 2025). "HALs exhibit distinct molecular profiles—including elevated EBV infection, a GCB-like phenotype, increased Ki67 AOD, and decreased BCL2 expression—that contribute to significantly poorer survival compared to HIV-negative lymphomas." (PMID 40496610, 2025). "Such dynamic lymphoma evolutionary process initiated by IGH::BCL2 provides a paradigm for investigations of clonal evolution in other lymphomagenic conditions." (PMID 39722652, 2025). "Unexpectedly, even though the incidence of lymphoma was low in Eμ-Bcl-2 transgenic mice, these animals developed with high incidence fatal autoimmune disease, resembling human systemic lupus erythematosus (SLE)." (PMID 40204952, 2025). "HALs also exhibit significantly higher expression of proliferation markers such as MYC (≥40% in 55% of cases) and BCL2 (≥50% in 65% of cases), meeting the criteria for double-expressor lymphoma (DEL) in a large proportion of cases." (PMID 40496610, 2025). "Andreas Strasser joined Suzanne Cory’s laboratory at WEHI and conducted a thorough characterization of several of the Eμ-Bcl-2 transgenic lines and the development of lymphoma in the Eμ-Myc/Eμ-Bcl-2 double transgenic mice." (PMID 40204952, 2025). "A combination of the BTK inhibitor Zanubrutinib and the BCL2 inhibitor navitoclax synergistically induced apoptosis and ferroptosis to suppress growth in double-hit lymphoma." (PMID 40332068, 2025). "To test and characterize the immunogenicity of TIS cells, we inoculated strain-matched mice with ex vivo-pre-treated (i.e. TIS) or untreated Eμ-myc;bcl2 lymphomas." (PMID 40159497, 2025). "It has been reported that BCL2 expression in lymphoma cells induces hypoxia-inducible factor-1 alpha (HIF1α)-mediated expression of VEGF, an angiogenic factor that promotes endothelial cell proliferation and migration." (PMID 39735667, 2025). "The cAMP–PKA–CREB pathway regulates mitochondrial function and promotes apoptosis in lymphoma cells through a mitochondria-dependent pathway, decreasing Bcl-2 expression and increasing Bax expression." (PMID 40832602, 2025). "In some types of leukemia and lymphoma, cancer cells evade the natural mechanism of apoptosis by overexpressing Bcl-2, leading to the oversurvival of cancer cells." (PMID 38921561, 2024). "Double-hit or triple-hit lymphomas, where there are chromosomal translocations involving MYC, BCL2 and/or BCL6 oncogenes, are associated with a higher risk of CNS recurrence." (PMID 38173015, 2024). "In this case, the presence of IGH super enhancers (at both joining and switch region) most likely drive constitutive BCL6 and BCL2 transactivation, hence the strong expression of both proteins in lymphoma cells." (PMID 38184753, 2024). "Many DLBCLs increase the levels of a protein called BCL2 that blocks lymphoma cell death and contributes to treatment resistance and relapse." (PMID 38893249, 2024). "Studies have pointed toward the development of more selective protein inhibitors in the BCL-2 family, including Bcl-2 and Mcl-1, to counteract the progression of lymphomas in patients." (PMID 39769118, 2024). "Although BCL2 acts as a pro-survival oncogene in lymphoma, it has been found to have a contradictory role as a suppressor gene in different types of tumors, such as BRCA." (PMID 39342122, 2024).
lymphoma (continued). "High-grade B cell lymphoma (HGBL) with translocations involving MYC and BCL2 is retained as a so-called double hit (DH) lymphoma, by the 5th edition World Health Organization (WHO) classification (2022)." (PMID 38914869, 2024). "Eμ-BCL2 mice occasionally develop lymphomas; moreover, in humans, a chromosomal translocation linking the IGH and BCL2 loci is associated with B lymphomas and CLL, and BCL2 is typically overexpressed in CLL." (PMID 38625151, 2024). "BH3-mimetics represent promising anti-cancer agents in tumors that rely on the anti-apoptotic function of B-Cell Lymphoma 2 (BCL2) proteins, particularly in leukemia and lymphoma cells primed for apoptosis." (PMID 38622118, 2024). "Navitoclax is another identified senolytic that eliminates senescent cells primarily through targeting the Bcl-2 family of anti-apoptotic proteins including Bcl-2 and Bcl-xl and has undergone phase II clinical trials for lymphoid cancers." (PMID 39483466, 2024). "Because prognosis of high-grade lymphoma depends upon various factors, we applied IHC markers BCL-2, MUM-1, and C-MYC to look for double hit and triple hit expressor lymphomas." (PMID 39347303, 2024). "By contrast, 204 genes associated with an unfavorable prognosis were also identified, including many genes involved in lymphoma growth and survival, such as Myc and Bcl2." (PMID 39684518, 2024). "For this, we performed RNA-seq profiling of sorted B220+ murine lymphoma cells at day 235, and then identified the set of genes repressed in BCL2 + CK relative to BCL2." (PMID 38570506, 2024). "The differential diagnosis of BL includes HGBCL/DLBCL with MYC and BCL2 gene rearrangements (either de novo or as a transformation of a follicular lymphoma), B-lymphoblastic leukemia/lymphoma and high-grade/large B-cell lymphoma with 11q aberrations." (PMID 37530792, 2024). "It is well known that, in most lymphomas, overexpression of the biomarkers Bcl-2 and Mcl-1 is promoted." (PMID 39769118, 2024). "It is worth noting that double-expressor lymphomas that overexpress MYC and BCL2 proteins are aggressive DLBCLs and are associated with a dismal prognosis." (PMID 39518937, 2024). "Venetoclax is a drug used to treat specific types of leukemia and lymphoma, known as a Bcl-2 inhibitor." (PMID 38921561, 2024). "A subtype of lymphomas is called a double-hit lymphoma, which forms when it contains MYC and either BCL2 or BCL6 mutations; this subtype is often seen in patients who have disease at the interference between Burkitt lymphoma and DLBCL." (PMID 39010207, 2024). "Of note, the SHM burden was significantly greater in BCL2 + CK lymphoma cells at both time points as compared to all other genotypes, suggesting these cells were more exposed to dark zone (DZ)-like proliferative bursting and AICDA activity." (PMID 38570506, 2024). "One common mechanism for evading apoptosis in cancers is the overexpression of BCL-2 proteins, observed in various cancers, such as prostate, colorectal, lung, gastric, breast, lymphoma, and leukemia." (PMID 39594670, 2024). "Recently, the renewed WHO classification removed BCL-6 from the classification, leaving only rearrangements of MYC and BCL2 to define double-hit lymphomas." (PMID 38397877, 2024). "Using cell numbers as a proxy for disease prognosis resulted in predictions that MYC + BCL2 DH lymphoma would have worse prognosis than MYC + BCL6 DH lymphoma." (PMID 38965209, 2024). "For example, hypermethylation of BCL-2, BAX, BAK, and PUMA promoter are implicated in prostate cancer, multiple myeloma, and lymphoma, highlighting the role of epigenetic alterations in apoptosis resistance." (PMID 39594670, 2024). "There was progressively greater abundance of lymphoma cells infiltrating solid organs in BCL2, BCL2 + C, BCL2 + K, and especially in BCL2 + CK animals." (PMID 38570506, 2024). "The presence of this translocation is consistent with the BCL2 gene expression detected in this cell line as well as in patients with lymphoma." (PMID 38397052, 2024).
lymphoma (continued). "Based on IHC findings in our study, only four cases were double hit lymphoma expressing BCL-2 with MUM-1/C-MYC positivity." (PMID 39347303, 2024). "These patients have previously been published as part of a prior study (n = 34) investigating MYC, BCL2, and BCL6 rearrangements, pathogenic variants of MYD88 and CD79B, and double-expressor lymphoma." (PMID 38542066, 2024). "The findings showed that the BCL2-CA genotype was significantly related to higher risks of lymphoma by 2.12 (95% CI = 1.19–3.77) among patients than the controls." (PMID 36831357, 2023). "We developed VavP-bcl2 transgenic, TFL deficit mice (Bcl2-Tg/Tfl-/-) to seek how TFL affects disease progression in this lymphoma model." (PMID 37304286, 2023). "Further characterisation of high-grade B-cell lymphoma achieved by next-generation sequencing, and mutations of MYC and BCL2 and/or BCL6 genes (“double-hit”-DHIT or “triple-hit”-THIT lymphoma) have been associated in various studies with a worse prognosis." (PMID 37240953, 2023). "In contrast to DLBCL/HGBL-MYC/BCL2, aggressive lymphomas with either large cell or high-grade morphology and an MYC/BCL6 double hit, but lacking BCL2 translocations, form a heterogeneous tumor category without indications of a unifying biology." (PMID 37190213, 2023). "ABT-737 was also one of the first developed Bcl-2 inhibitors that demonstrated efficient activity against lymphoma." (PMID 37834104, 2023). "The MYC protein promotes cell proliferation, while the antiapoptotic BCL2 protein contributes to accelerating lymphoma progression by interaction with other oncogenes, especially MYC." (PMID 37925380, 2023). "LFPRLR knockdown in lymphoma-prone mice reduces B-cell numbers and their expression of BCL2 and TCL1." (PMID 36941341, 2023). "Consistently, our results showed highly increased expression in relapsed and refractory DLBCL but a wide range of Bcl-2 expression in lymphoma cells including the patients who achieved CR (remission)." (PMID 37627134, 2023). "We show that B cell lymphomas are ill-equipped for acute, therapy-induced polyploidy and that BCL-2 inhibition further enhances the removal of polyploid lymphoma cells." (PMID 36934096, 2023). "CDC6 promotes lymphoma cell survival and prevents cell apoptosis, possibly through cell cycle regulation, Bcl2 upregulation and downregulation of Bax and INK4 and E-cadherin." (PMID 37833632, 2023). "Between lymphoma patients and controls, there was statistically significant variance in the BCL2-938 C > A gene." (PMID 36831357, 2023). "The additional Fluorescence In Situ Hybridization (FISH) analysis demonstrated MYC and BCL2 rearrangements and is consistent with high‐grade B‐cell lymphoma with MYC and BCL2 rearrangements (“double‐hit” lymphoma)." (PMID 37206289, 2023). "Here, we report a therapeutic combination of inhibitors of the Polo-like kinase 4 and BCL-2 that trigger genomic instability and cell death in aggressive lymphomas." (PMID 36934096, 2023). "Only a very small proportion of individuals with IGH::BCL2 will eventually develop a lymphoma, with the majority being follicular lymphoma (FL)." (PMID 37345526, 2023). "Contrary to controls, where genotype CC was more prevalent (54.28%), lymphoma patients were more likely to have the CA genotype of BCL2-938 C > A (58%), according to research." (PMID 36831357, 2023). "The unavailability of BIM (Bcl-2-interacting mediator), a pro-apoptotic protein, and the availability of overexpressed Bcl-2 were reported to increase c-myc oncogene-mediated lymphoma development which strongly indicates that apoptosis evasion promotes cancer." (PMID 36830564, 2023). "ASTCT recommends upfront auto‐HSCT only with c‐myc and bcl‐2 and/or bcl‐6 rearrangements (high‐grade lymphomas)." (PMID 36855295, 2023). "They chose the population of study to be high-risk lymphoma patients bearing MYC rearrangements or translocations (i.e., HGBL) or overexpression of MYC or BCL2." (PMID 37457123, 2023).
lymphoma (continued). "As expected, characteristic translocations of the 3′ end of BCL2 to the IGH locus were detected in all lymphomas, with MYC translocations to various partner loci seen upon transformation to DHL." (PMID 38049665, 2023). "The reason for this is that aggressive lymphomas with a MYC/BCL2 double hit form a homogeneous group with respect to GEPs and the mutational profile, whereas MYC/BCL6 DH lymphomas are heterogeneous in nature." (PMID 37190213, 2023). "We examined the responses of sgTfap4/Eμ-MYC/Cas9 and sgControl/Eμ-MYC/Cas9 lymphoma cell lines to the BH3 mimetic drugs ABT-199/Venetoclax or S63845 that inhibit BCL-2 or MCL-1, respectively." (PMID 36894688, 2023). "At many loci, we find lymphoma transformation-associated aSHM cluster around boundaries of TADs containing known aSHM targets including DTX1, BCL2 and PAX5." (PMID 38049665, 2023). "This approach enabled the clustering of lymphomas with co-occurring MYD88- and CD79B mutations (MCD), BCL6 rearrangements and NOTCH2 mutations (BN2), EZH2 mutations and BCL2 rearrangements (EZB), as well as NOTCH1 mutations (N1)." (PMID 38124747, 2023). "Predicting MYC and BCL2 double-expressor lymphoma prognosis using the system immune-inflammatory index (SII) and prognostic nutritional index (PNI) (DEL)." (PMID 37873542, 2023). "In each of these scenarios, the two lymphomas often appear to be clonally related by analyses of IGH::BCL2 and/or rearranged IG genes." (PMID 37345526, 2023). "A higher risk of lymphoma, notable NHL, was shown to be related to variations in the antiapoptotic genes BCL2-938 C > A, MCL1-rs9803935 T > G, survivin-rs17882231 G > C, and BIRC5-rs9904341 G > C, particularly among men aged more than 45 years." (PMID 36831357, 2023). "Subsequent data described, that some rare cases with 11q gain/loss have simultaneously rearrangement or amplification of MYC and are diagnosed as BL or HGBL,NOS, or even double-hit lymphoma with BCL2 rearrangement." (PMID 37941034, 2023). "Combined with BCL2 deregulation, KMT2D mutation is sufficient for lymphoma development in vivo, recapitulating the co-presence of KMT2D mutation and BCL2 translocation in human DLBCL." (PMID 36765793, 2023). "We then tested the combination of PLK4 and BCL-2 inhibitors in a primary transplanted patient-derived GCB-DLBCL lymphoma model (PDX)." (PMID 36934096, 2023). "In four cases, the two lymphomas were clonally related, as shown by identical IGH::BCL2 and/or rearranged IG genes or shared mutations." (PMID 37345526, 2023). "The BCL-2 over-expressing lymphomas from our mice are committed to the B cell lineage, and can readily be grown as cell lines." (PMID 35961968, 2022). "The presence of oxidative DNA damage biomarkers identified a poor prognosis double expresser (DE)-DLBCL subset, characterized by relatively higher BCL-2 gene expression levels and enrichment for DH lymphomas." (PMID 34304248, 2022). "Venetoclax is a B-cell lymphoma (BCL-2) homology domain-3 (BH-3) mimetic, selective B-cell lymphoma (BCL-2) inhibitor used in the treatment of lymphomas and leukemias." (PMID 35498039, 2022). "In DHL/THL model, OTX015 (Birabresib) combined with BCL2 antagonist (such as Venetoclax) synergically inhibited the malignant proliferation of DHL/THL cells, supporting the combining use of BETi and BCL2 inhibitors against MYC-driven lymphoma." (PMID 35303910, 2022). "Lymphomas with rearrangements of MYC with BCL2 and/or BCL6 are called “double-hit lymphomas”(DHL) or “triple-hit lymphomas”(THL)." (PMID 35498426, 2022). "Double expressors are defined as having expression of both MYC ≥ 40% and BCL2 ≥ 50% within lymphoma cells." (PMID 35626243, 2022). "It is a selective Bcl‐2 inhibitor that is clinically used for the treatment of patients with lymphomas and leukemias." (PMID 34173723, 2022). "In line with our HTS data, the most favorable interactions were observed in BCL-2 positive DLBCL cell lines, including different BCL-2 rearranged and DH lymphoma models." (PMID 34304248, 2022).
lymphoma (continued). "MYC is also closely related to BCL2, and most patients with refractory DLBCL will exhibit double-hit lymphoma (MYC-BCL2 rearrangement) or double protein expression lymphoma (MYC-BCL2 high expression)." (PMID 35069971, 2022). "These lymphomas are often called double-hit lymphomas, or triple-hit lymphomas if there are both Bcl-2 and Bcl-6 rearrangements in addition to the MYC rearrangement." (PMID 36618391, 2022). "We also reported that Tigecycline and venetoclax cooperated in killing MYC/BCL2 double‐hit lymphoma cells, and showed synergy against DHL in a preclinical setting." (PMID 34632715, 2022). "The dual-targeting approach significantly enhances internalization of BCL-2 siRNA in lymphoma and leukemia cells, which leads to significant downregulation of BCL-2 expression." (PMID 35209102, 2022). "Eμ-Myc lymphoma cells treated with M-100 de-repressed Bbc3 as well as Pmaip1 and repressed Bcl2 expression." (PMID 36068335, 2022). "This molecule shows synergy with select BH3‐mimetic drugs in killing cancer cells, and in particular with the BCL2 inhibitor venetoclax against the aggressive double‐hit lymphoma subtype, with promising antitumoral effects in preclinical models." (PMID 34632715, 2022). "The second strategy is the combination of GSK-591 with the BCL-2 inhibitor, venetoclax, which induces apoptosis of lymphoma cells." (PMID 36167829, 2022). "Genetic rearrangements of MYC and BCL2 and lymphoma derived from MYC and BCL2 co-expression have received increasing attention in recent years." (PMID 35198451, 2022). "Of note, we identified one BCL-2 expressing lymphoma cell line which is fully resistant to MCL-1 inhibitor treatment, but sensitive to venetoclax." (PMID 35961968, 2022). "C-MYC/BCL-2 double-hit lymphoma has been recognized as a chromosomal break involving MYC and BCL-2, which is very rare, representing 3% of all DLBCL cases." (PMID 35875161, 2022). "Such process also contributes to increased GC formation, pro-proliferative cellular profile, inhibition of tumor-suppressive pathways, accelerated lymphoma development, and even malignant transformation when cooperate with BCL2." (PMID 35303910, 2022). "A recent study showed that nonbenzodiazepine BETi, PLX-2853, synergize with venetoclax to induce apoptosis in MYC-driven lymphomas with high BCL2 expression." (PMID 35303910, 2022). "Third, IACS‐010759 showed synergy with BH3‐mimetic compounds that inhibit either BCL2 or Mcl‐1, allowing context‐dependent killing of lymphoma cell lines." (PMID 34632715, 2022). "In line with this, it has been reported that NQ triggers cell death in L5178Y murine lymphoma cells and SA causes apoptosis by downregulation of the anti-apoptotic factors MCL-1/BCL-2." (PMID 35684504, 2022). "Because BCL2/JH rearrangement can be found only in 60% of FL and the assessment of IgH rearrangement in this lymphoma is often difficult due to its hypermutated status, the possibility of assessing different molecular markers is intriguing." (PMID 35741115, 2022). "The double-hit status (simultaneous translocations of MYC and BCL2 or BCL6) was determined in 146 lymphomas, with a positive result in 11 cases (7.5%)." (PMID 34708297, 2022). "Upregulated expression of the anti-apoptotic BCL2 oncogene is a common feature of various types of B-cell malignancies, from lymphoma to leukemia or myeloma." (PMID 36358756, 2022). "This upregulation observed in some human lymphomas has paralleled recent research in veterinary medicine regarding Bcl-2 immunoexpression in feline lymphomas." (PMID 35448666, 2022).